TNF (tumor necrosis factor)
Diseases named in the same sentence as TNF in open-access papers (continued):
Sharing a sentence is not in itself a finding about the gene and the disease.
type 2 diabetes (continued). "Met along with probiotic showed inhibitory effect by downregulating the expression of the inflammatory cytokines like TNF-α in colorectal cancer (CRC) and type 2 diabetes." (PMID 33953643, 2021). "In a study of 367 Mexican–Americans, type 2 diabetes was strongly related to elevated levels of IL-6, leptin, CRP and TNF-α, whereas higher glucose levels correlated positively and linearly with high levels of IL-6 and leptin." (PMID 32751810, 2020). "The present results revealed that B. vernae extract could significantly reduce the TNF-α, IL-1β, and IL-6 levels of diabetic rats, suggesting that B. vernae might have potential anti-inflammation activity, which is beneficial to improve the inflammatory state of type 2 diabetes." (PMID 32636751, 2020). "The present study sought to evaluate the beneficial effects of histidine (His) on oxidative stress, tumor necrosis factor alpha (TNF-α), renal histological alterations and anti-oxidant enzymes gene expressions in type 2 diabetic rats." (PMID 32695286, 2020). "In type 2 diabetes, there is a correlation between sRAGE and serum levels of macrophage colony-stimulating factor (MCSF) as well as tumor necrosis factor alpha (TNF-alpha)." (PMID 32727002, 2020). "Importantly, exposure to inflammatory cytokines, such as TNF and IL-6, and activation of NF-κB in muscle can decrease oxidative metabolism, induce atrophy, and prevent insulin-stimulated Akt phosphorylation, all of which are factors in the development of type 2 diabetes and metabolic syndrome." (PMID 32591558, 2020). "In the present study, we demonstrated that hepatic inflammation was increased in HFD/STZ-induced type 2 diabetic mice as evidenced by the upregulation of TLR4, MCP-1, and TNF-α mRNA expression." (PMID 32182914, 2020). "According to the authors, naringin attenuated hyperglycemia-mediated oxidative stress parameters (MDA and NO) and pro-inflammatory cytokine (TNF-α and IL-6) secretion and production in HFD/STZ-induced type 2 diabetic rats." (PMID 32977511, 2020). "Correlation analysis between the biomarkers (Tf, IgG, NGAL, and TNF-α) and UACR in patients with type 2 diabetes." (PMID 31218128, 2019). "In response to acute hyperinsulinemia, a decrease of TNFα, IL-8, and IL-18 circulating levels was observed in healthy lean subjects, while in first-degree relatives (FDR) of type 2 diabetic patients, this anti-inflammatory response was blunted." (PMID 30983877, 2019). "These include leptin, myostatin, adiponectin, and tumor necrosis factor (TNF)-α, all of which are involved in the development of cardiometabolic diseases, such as type II diabetes, and cardiovascular disease (CVD)." (PMID 30382930, 2018). "In a rat model of type 2 diabetes, GW0742 was shown to reduce the proinflammatory cytokines tumor necrosis factor-α (TNF-α) and monocyte chemoattractant protein-1 (MCP-1) in liver tissues, in conjunction with reduced hepatic fat accumulation." (PMID 30373124, 2018). "In ourstudies, circulating levels of MCP-1 and TNF-α, as well as insulin were greatly elevatedin mice fed on HFD for 15 weeks, indicating a proinflammatory state and insulinresistance seen in type-2 diabetes." (PMID 28076453, 2017). "In the present study, we determined the effects of metformin on the levels of pro-inflammatory cytokines (i.e., IL-6, TNF-α, and MCP-1) and anti-inflammatory mediator IL-10 in blood and urine of patients with type 2 diabetes." (PMID 27904436, 2016). "Clinically NF-κB related cytokines, TNF-α, IL-6, and MCP-1, were found increased in patients with type 2 diabetes." (PMID 27656261, 2016). "In the present study, we determined the effects of metformin with different doses and durations on the levels of pro-inflammatory cytokines (i.e., IL-6, TNF-α, and MCP-1) and anti-inflammatory mediator IL-10 in blood and urine of patients with type 2 diabetes." (PMID 27904436, 2016).
type 2 diabetes (continued). "In comparison with gliclazide, acarbose, and repaglinide, metformin reduced the levels of serum IL-6, TNF-α, and urinary MCP-1 in patients with type 2 diabetes." (PMID 27904436, 2016). "Our results indicated that significant increases in the levels of pro-inflammatory cytokines, TNF- α IL-6 and also CRP were observed in obese and type 2 diabetic rats and were consistent with other studies." (PMID 26003803, 2015). "Real-time PCR and western blotting assays revealed that type 2 diabetes significantly up-regulated the expression levels of inflammatory factors (ICAM-1, TNF-α and PAI-1) and nitrosative damage markers (3-NT and MDA) in the kidney." (PMID 24651118, 2014). "With the exception of CCL-2 (p = 0.09), differences in TNF-α (p < 0.0001), hs-CRP (p < 0.05), IL-6 (p < 0.05) and adiponectin remained significant after excluding subjects with type 2 diabetes (n = 7) from the NASH cohort." (PMID 24962805, 2014). "Interestingly, we have previously demonstrated that monocyte-enriched mononuclear cells from individuals with type 2 diabetes show increased levels of visfatin, resistin, TNF-α, IL-6, and IL-1β mRNA expression indicating that hyperinsulinemia and hyperglycemia could enhance cytokine production." (PMID 23484124, 2013). "Low-grade inflammation has been reported in FDR of type 2 diabetics, and inflammatory markers such as hsCRP, IL6 and TNFα have been reported to induce SVI in various stress related disorders." (PMID 24265679, 2013). "In JNK-deficient mice, the expression of proinflammatory cytokines (including TNFα, IL-6, and MCP-1) induced by obesity is suppressed, and this can promote protection from insulin resistance and T2DM (type 2 diabetes mellitus)." (PMID 23762873, 2013). "Recently we demonstrated that circulated TNFα and its two receptors were the strongest predictors of progression to CKD3 in Type 1 diabetes and ESRD in Type 2 diabetes." (PMID 23505438, 2013). "In conclusion, our results showed that urinary levels of the proinflammatory marker TNF-α and the tubular marker NGAL were elevated and correlated with albuminuria in patients with type 2 diabetes." (PMID 24250725, 2013). "The metabolic activities of TNFα are mainly mediated through TNFR2 (type 2 receptor for TNFα), providing the inflammation-metabolic interface in type 2 diabetes." (PMID 21849023, 2011). "In this paper, recent findings regarding the effects of cytokines including IL-1β, IFN-γ, TNF-α, leptin, resistin, adiponectin, visfatin, and PANDER on pancreatic β-cell dysfunction and type 2 diabetes will be summarized and discussed." (PMID 21113299, 2010). "Plasma levels of C-reactive protein and pro-inflammatory cytokines, such as tumor necrosis factor (TNF)-α and interleukin (IL)-6, are elevated in subjects with essential hypertension, coronary heart disease and type 2 diabetes." (PMID 20664801, 2010). "Peripheral levels of Interleukin-1β (IL-1β), Interleukin-6 (IL-6), and tumor necrosis factor-α (TNF-α) are elevated during first-episode psychosis and psychotic relapses in schizophrenia, as well as in the pathogenesis and complications of type 2 diabetes." (PMID 40426670, 2025). "Participants with type 2 diabetes who consumed oleocanthal-enriched HP-EVOO experienced enhanced antiplatelet effects, lower inflammatory cytokine levels (TNF-α, IL-1β, and IL-6, p < 0.05) and enhanced anti-inflammatory IL-10 concentration (p = 0.032) compared to butter, olive oil and EVOO groups." (PMID 40136590, 2025). "We found that at the end of treatment, XOMA052 was able to alleviate chronic inflammation in type 2 diabetes by down-regulating the production of IFN-γ and IL-17a in peripheral blood, reducing inflammatory cytokines TNF-α, IL-1β, and IL-6, and reducing β cell apoptosis and promoting proliferation." (PMID 40066372, 2025).
type 2 diabetes (continued). "TNF-α, in particular, impairs insulin signaling by promoting serine phosphorylation of IRS-1, while IL-1β exacerbates pancreatic β-cell dysfunction and contributes to the development of type 2 diabetes." (PMID 40867531, 2025). "No significant change in TNF-α levels was detected after 6 weeks of high-dose 20 mg per day tadalafil in patients with type 2 diabetes." (PMID 40806281, 2025). "We have found that MSCs can inhibit macrophage generation of the inflammatory cytokines TNF-α and ROS, which could implicate the potential anti-inflammatory functions of MSC protecting β-cell functions in type 2 diabetes." (PMID 38533089, 2024). "In particular, oral administration of Bergacyn® reduced oxidative stress (GPx, SOD and MDA) and inflammatory biomarkers (TNF-α), contributing to a significant improvement of vascular inflammation and NO-mediated vasodilation in patients with NAFLD and type 2 diabetes." (PMID 38257152, 2024). "These researchers concluded “that targeting cytokines, cytokine receptors, and inflammation-associated nuclear transcription factors, such as IL-1β, IL-αR, TNF-α, and NF-kB alone or in combination, can significantly reduce the level of FPG, HbA1c, and CRP in patients with type-2 diabetes." (PMID 39199336, 2024). "Metformin has previously been shown to decrease circulating levels of CRP, IL-6, and TNF-α in patients with type 2 diabetes, however this finding was not replicated in our subjects who were nondiabetic and nonprediabetic." (PMID 37131271, 2023). "The results from this study suggested that ALA treatment may preserve soleus muscle mass, alleviate muscle atrophy by suppressing the TNF‐α/JNK pathway, and ameliorate the PI3K/AKT pathway in HFD/STZ‐induced type 2 diabetic rats." (PMID 37051351, 2023). "However, in our cohorts, pro-inflammatory cytokines IL-6, IL-8, TNF-α, and IFN-γ were significantly higher in type 2 diabetes compared to type 1, which is consistent with previous findings." (PMID 37189645, 2023). "In the present study, ALA ameliorated levels of TNF‐α and pAKT/AKT ratios in muscle tissues, suggesting that ALA may alleviate inflammation by suppressing the TNF‐α/JNK pathway in muscle of type 2 diabetic rats." (PMID 37051351, 2023). "TNF, NFkB complex, NFkBIA, NFkB1 and RELA were also involved in type 2 diabetes signaling." (PMID 37047308, 2023). "This evidence further strengthens the possibility of a link between TNF-α and TCF7L2 which may play an important role in the co-existence of malaria and type 2 diabetes." (PMID 37215099, 2023). "In type 2 diabetes and HTN, obesity and overweight, insulin resistance, and overexpression of pro-inflammatory proteins including C-reactive protein (CRP) and cytokines (IL-1β, IL-6, and TNF-α) contribute to chronic inflammation." (PMID 35361279, 2022). "In human studies, plasma FKN levels were significantly higher in type 2 diabetes (T2D) patients when compared with non-diabetics and was found to correlate positively with many pro-inflammatory cytokines, including TNF-α." (PMID 33904577, 2021). "Metformin, a prescribed drug for type 2 diabetes, has been reported to protect CD8+ tumor-infiltrating lymphocytes from apoptosis and exhaustion characterized by decreased production of IL-2, TNF-α, and interferon-γ (IFN-γ) via AMP-activated protein kinase (AMPK) activation." (PMID 34880864, 2021). "IM patients with type 2 diabetes (main group) have a 2.7 times increase in CRP content, 4.4 and 3.1 times in proinflammatory IL-6 and TNF-α, respectively, as well as anti-inflammatory IL-10 concentration of 1.9 times higher relative to the indicators in the control group." (PMID 32341698, 2020). "The purpose of this research is to study the dynamics of C-reactive protein (CRP), IL-6, TNF-α, and interleukin-10 (IL-10) in patients with type 2 diabetes who underwent non-Q-myocardial infarction (non-Q-IM), against the background of ALA." (PMID 32341698, 2020).
type 2 diabetes (continued). "To further understand how AGEs accelerate diabetic AS, we investigated the plasma level of AGEs, RAGE, T-lymphocyte subsets, and inflammatory cytokines including tumor necrosis factor alpha (TNF-α) and interferon gamma (IFN-γ) in the peripheral blood of elderly patients with type 2 diabetes." (PMID 33817224, 2020). "For example, the pro-inflammatory cytokine TNF-α contributes to the development and progression of inflammation-related diseases, such as nonalcohol steatohepatitis, type 2 diabetes, and cancer, by promoting necrotic cell death." (PMID 32978261, 2020). "After the identification of the improving effect of JQJT tablets on the gut barrier, since insulin resistance was closely related to the low level inflammatory response in type 2 diabetes we evaluated the effect of JQJT tablets on inflammation by checking the levels of IL-6, TNF-α, and MCP-1." (PMID 30733971, 2019). "There is also a relationship between high TNFα levels and the presence of MetS components in elderly people without a diagnosis of type 2 diabetes or cardiovascular disease." (PMID 30383538, 2018). "In type 2 diabetic patients with coronary heart disease, the supplementation with L. usitatissimum oil (1000 mg/day for 12 weeks) increased gene expression levels of PPAR-γ and downregulated gene expression of lipoprotein(a), IL-1 and TNF-α." (PMID 29300317, 2018). "The TNF-α level in GCF and serum is an inflammatory marker in CP and type 2 diabetes patients." (PMID 28934245, 2017). "In addition, the levels NF-κB and TNFα, which are downstream mediators of the TLR4 pathway, were reported to be upregulated in the retina of type 2 diabetic rats." (PMID 26997759, 2016). "Consistent with this observational data, we previously found that almonds decreased IL-6 and CRP, and TNF-α in Chinese patients with type 2 diabetes but did not affect ICAM-1 or VCAM-1." (PMID 26080804, 2015). "Lowering resistin by RNA oligo with reduction of circulating TNF-α and IL-6 might provide a new insight into managing inflammation-mediated diseases, such as NAFLD, type 2 diabetes, and cardiovascular disease." (PMID 25922835, 2015). "We hypothesized that sodium salicylate would reduce IKKβ, leading to reduced TNFα and improved insulin signaling in the BBZDR/Wor obese rat model of type 2 diabetes." (PMID 25874611, 2015). "Recently, inflammatory mediators, including TNF-α, interleukin-1, 6, 13 and 17, chemokines such as MIP-1α, RANTES and fractalkine, have been found to be increased in the DRG of Zucker diabetic fatty (ZDF) rats, an established model for type II diabetes." (PMID 24961298, 2014). "Furthermore, recent studies in patients with type 2 diabetes showed that insulin treatment decreased expressions of inflammatory cytokines, such as MCP-1, ICAM-1, soluble VCAM-1 (sVCAM-1), TNF-α, and IL-6." (PMID 23862164, 2013). "The present study was designed to verify the feasibility of using the tear TNF-alpha assay as a novel biomarker to assess the degree of eye involvement in type 2 diabetic patients with and without proliferative diabetic retinopathy." (PMID 24259948, 2013). "It is important to mention that in this type 2 diabetes obese animal model, leptin is absent and there is an increase in circulating TNFα." (PMID 22662132, 2012). "As a whole, our results suggest that the effect of cytokines (IL-1β, IL-6 and TNF-α) on the incidence of type 2 diabetes might be mediated by other factors; they also suggest that these markers do not improve risk prediction as assessed by a validated type 2 diabetes risk score." (PMID 23251619, 2012). "In the present study, plasma TNF-α levels reached statistical significance 9 h after AOM administration and clearly preceded the onset of coma and massive hepatocyte cell death which occurred only at coma stages of HE, as shown by large increases in ammonia and transaminase levels." (PMID 23166746, 2012).
type 2 diabetes (continued). "In subjects with and without type 2 diabetes, PPARD +294T>C was associated with BMI, HDL-C, leptin, and TNF-alpha and was dependent on gender." (PMID 23039238, 2012). "The cascade of TNF-α and IL-6 elevation leads to increments in hsCRP and fibrinogen, with resulting adhesion molecule expression, and may facilitate development of type 2 diabetes mellitus (T2DM) as well as CHD." (PMID 22482065, 2011). "Blood levels of IL-6, but not TNFα have also been reported to be an independent predictor of type 2 diabetes after adjustment for BMI." (PMID 20525188, 2010). "We tested association of nine single nucleotide polymorphisms (SNPs) from TGFβ1, TNFα, CCR2 and CCR5 genes among individuals with type-2 diabetes with and without renal insufficiency." (PMID 17428349, 2007). "The present data is consistent with the idea that Type 2 diabetes LDL could increase ADAM17 activity in THP-1 monocytes, and their ability to shed TNF-α and VCAM-1." (PMID 17714581, 2007). "Consistent with our results, N-acetylcysteine treatment in type 2 diabetic mice has been shown to effectively preserve the expression of antioxidant enzymes, attenuate ROS production in diabetic ischemic limbs, and reverse the levels of phosphorylated IRS-1, Akt, eNOS, and plasma TNF-α." (PMID 39125400, 2024). "Thus, the aim of this work is to identify the effects of different types of exercises on the expression of the CHRNA7, CHRFAM7A and tumor necrosis factor-α (TNF-α) in leukocytes of healthy normal weight (HNW), and overweight with type 2 diabetes (OT2D) individuals." (PMID 36831101, 2023). "On contrary, TNF-α neutralization in type 2 diabetes patients failed to affect insulin sensitivity." (PMID 37168278, 2023). "Substituting one serving of red meat with one serving of legumes in DASH diet, at least five days a week, could improve the hs-CRP, TNF-α, IL-6, and MDA in participants with type 2 diabetes regardless of having rs7903146 risk or non-risk allele." (PMID 35585604, 2022). "Also, higher levels of tumor necrosis factor (TNF)- α, as found in type 2 diabetes, may induce NFκB and bone morphogenetic protein-2, both involved in PiT-1 upregulation." (PMID 35477475, 2022). "Elevated levels of interleukin-1β (IL-1β), interleukin-6 (IL-6), interleukin-8 (IL-8), tumor necrosis factor α (TNF-α), soluble interleukin-2 receptor (sIL-2R), and nitric oxide (NO) correlating with both the presence and the severity of DR were found in the serum of patients with type 2 diabetes." (PMID 36012690, 2022). "Moreover, similar frequencies of CD4+T cells that produced individual cytokines or co-produced TNFα and IFNγ following S1 or S2 peptide stimulation were detected in responders with or without type 2 diabetes." (PMID 36304475, 2022). "In conclusion, substituting one serving of red meat with one serving of legumes in DASH diet, at least five days a week, could improve the hs-CRP, TNF-α, IL-6, and MDA in participants with type 2 diabetes regardless of having rs7903146 risk or non-risk allele." (PMID 35585604, 2022). "Ventricular myocytes isolated from control rats were incubated 24 h in DMEM supplemented with either plasma obtained from non-diabetic animals; or plasma extracted from type 2 diabetic animals, with or without added TNFα (50 μM) and IL-1b (50 μg/mL) receptor blockers." (PMID 34202017, 2021). "Similarly, a recent systematic review and meta-analysis involving 685 individuals with prediabetes and Type 2 diabetes revealed that ω-3 PUFA supplementation for a period of 12–24 weeks increased levels of adiponectin and reduced levels of a proinflammatory cytokine, TNFα." (PMID 33573042, 2021). "Additionally, our results revealed that B. vernae extract or metformin treatment for 30 days significantly decreased (P < 0.01) serum FBG, INS, HOMA-IR, GSP, TNF-α, IL-1β, and IL-6 levels, whereas increased serum ISI levels (P < 0.01) in type 2 diabetic rats, compared with the model group." (PMID 32636751, 2020).